ANKRD30BP3 (ANKRD30B pseudogene 3)
Gene: Transcribed unprocessed pseudogene on chromosome 10 (45,156,775 to 45,176,925, forward strand). Ensembl gene ENSG00000230501.
Diseases named in the same sentence as ANKRD30BP3 in open-access papers:
ANKRD30BP3 is named in the same sentence as 1 disease in open-access papers, as found by Europe PMC text mining. Sharing a sentence is not in itself a finding about the gene and the disease. The quoted sentences say what the papers report.
glioma (1 paper, 2026). A benign or malignant brain and spinal cord tumor that arises from glial cells (astrocytes, oligodendrocytes, ependymal cells). "In this study, we demonstrated that glioma CEBPD directly binds to and activates the promoter regions of miR-4257 and miR-3156, located within the genes ADAMTSL4 and ANKRD30BP3, respectively." (PMID 41736026, 2026).